RNU6-837P (RNA, U6 small nuclear 837, pseudogene)
Gene: Small nuclear RNA gene on chromosome 12 (17,071,398 to 17,071,505, reverse strand). Ensembl gene ENSG00000212358.
Homologues: Orthologues: chimpanzee U6 (98% identical), rabbit U6 (62% identical), guinea pig U6 (58% identical), mouse Gm22476 (58% identical), mouse Gm26133 (58% identical), rat LOC120099053 (56% identical). Paralogues in human: RNU6-549P (75% identical), RNU6-1029P (74% identical), RNU6-476P (74% identical), RNU6-1158P (73% identical), RNU6-1263P (73% identical), RNU6-335P (73% identical), RNU6-43P (73% identical), RNU6-468P (73% identical), RNU6-1122P (72% identical), RNU6-140P (72% identical), RNU6-185P (72% identical), RNU6-20P (72% identical), and 1287 more.